FOXO1 (forkhead box O1)
Diseases named in the same sentence as FOXO1 in open-access papers (continued):
Sharing a sentence is not in itself a finding about the gene and the disease.
Obesity (continued). "Here, the authors show the transcription factor FoxO1 negatively regulates tyrosine hydroxylase expression in midbrain dopaminergic neurons, and plays an important role in regulation of glucose homeostasis, energy expenditure, and resistance to diet-induced obesity." (PMID 27681312, 2016). "This FoxO1-SNARE proteins axis represented a possible link between metabolic dysregulation and inflammatory amplification in obesity-related SAP." (PMID 40806352, 2025). "Third, the possible regulatory effect of FoxO1 on lysosome-localized SNARE proteins and other autophagic factors in obesity-related SAP needs further investigation." (PMID 40806352, 2025). "PI3K/AKT was suggested to regulate glucose metabolism through Forkhead box protein O1 (FoxO1) and glycogen synthase kinase 3 (GSK-3) and lipid metabolism through mammalian target of rapamycin complex 1 (mTORC1) and SREBP in obesity and T2DM." (PMID 39413106, 2024). "Therefore, we aimed to characterize if the expression levels of FOXO1 and SIRT1 in PBMCs in postmenopausal women with overweight/obesity are associated with MASLD risk biomarkers/indicators, and whether they can be modulated by DHA-rich n-3 PUFA supplementation and/or resistance training." (PMID 39264516, 2024). "Sirt1 plays a positive role in metabolic disorders such as obesity and T2DM through deacetylating FOXO1 to alleviate oxidative stress." (PMID 37329278, 2023). "FoxO1 ablation in POMC neurons increases CPE and α-MSH resulting in reduced food intake and protection from diet-induced obesity (DIO) weight gain." (PMID 37941908, 2023). "In mouse models of obesity, NOTCH signaling was found to regulate hepatic glucose production in a Forkhead box protein O1 (FOXO1)-dependent manner." (PMID 35805998, 2022). "Selectively suppressing FoxO1 activity through the inhibition of FTO by entacapone provides the possibility to treat type II diabetes and obesity." (PMID 31936903, 2020). "As these signaling pathways are blunted in obesity, further research efforts have been made to discover therapeutic agents to improve leptin sensitivity focusing on JAK-STAT and PI3K-Akt-FoxO1." (PMID 30935076, 2019). "Consequently, we postulated that targeted endothelial-specific depletion of FoxO1 would provoke capillary growth, preventing obesity-driven adipose tissue dysfunction, and provide a valuable tool to unmask the role of the microvascular endothelium metabolism in the pathophysiology of obesity." (PMID 30511639, 2018). "In the present study, for the first time, we investigated the effects of high-fat diet-induced obesity on MKP-3 content, and FoxO1 and Erk phosphorylation in the hypothalamus of mice." (PMID 29062272, 2017). "This study provides the first evidence of the synergistic regulation of the PI3K/AKT/FoxO1 pathway and gut microbiota restructuring by WSP, establishing a scientific foundation for valorizing walnut-processing waste into nutraceuticals against obesity." (PMID 41888130, 2026). "In conclusion, obesity-induced impaired autophagic flux and autophagosome–lysosome fusion in ATMs are potentially regulated via autophagosome-located SNARE proteins and the transcription factor FoxO1." (PMID 40806352, 2025). "In obesity and T2DM, CD36 becomes constitutively localized at the membrane through S-acylation by zinc finger DHHC-type palmitoyltransferase 4 (zDHHC4), which is upregulated by forkhead box protein O1 (FoxO1) signaling." (PMID 41002965, 2025). "Another important finding is that FoxO1-KOMPOA exhibits strong anti-obesity effects during HFD feeding in female but not male mice." (PMID 40667056, 2025). "Obesity may also play a role in the development of airway fibrosis, contributed to by factors such as TGF-β1, MMP-9, and FoxO1." (PMID 38562155, 2024). "In turn, PPARG and other mitochondrial-rated enzymes are shown to be governed by FOXO1 in this type of obesity and not in stress-induced obesity." (PMID 39062927, 2024).
Obesity (continued). "In individuals with obesity, both the mRNA levels and protein expression of FoxO1 were significantly increased compared to their non-obese counterparts." (PMID 38562155, 2024). "The protein expression and modifications of FoxO1 could be greatly altered under a variety of disease conditions including infection, ischemic reperfusion injury (IRI), allergic asthma, obesity and tumorigenesis." (PMID 35993049, 2022). "To date, however, the potential obesity-FoxO1 axis has not been explored in the context of the developmental origin of CLD." (PMID 35896539, 2022). "Taken together, these findings disclose that PI3K/Akt/FoxO1 pathway may be involved in the differentiation and proliferation of Th17 and Treg cells under the context of T2DM and obesity." (PMID 36463128, 2022). "No similar effects were observed after blocking FOXO1 in the normal diet, non-obese control group, thus pointing to a possible therapeutic approach against clinical obesity." (PMID 33806509, 2021). "FoxO1 protein was present in isolated nuclei irrespective of the feeding conditions or the degree of obesity although 24-h fasting modestly increased the nuclear FoxO1." (PMID 34728642, 2021). "Therefore, both Foxo1 and Foxo3 in CD4+ T cells should be molecular targets for the prevention and treatment of obesity." (PMID 31756626, 2019). "Nevertheless, to our knowledge, the contribution of FoxO1 signaling to vascular remodeling during obesity has not been addressed experimentally." (PMID 30511639, 2018). "Expression of forkhead transcription factors: energy metabolism pathway: In this study, we quantified the expression of FOXO1 and FOXO3A genes in whole blood cells of four groups of patients with NDs, obesity, diabetes type II, and depression and compared them with the normal population." (PMID 29736225, 2017). "Thus low expression of SIRT1 and Foxo1 leads to impaired Foxo1-C/EBP-α complex formation, which contributes to the diminished adiponectin expression in obesity and type 2 diabetes." (PMID 23843680, 2013). "Low expression of SIRT1 and FOXO1 can lead to impaired FOXO1-CEBPA complex formation, which might contribute to the diminished adiponectin expression in obesity." (PMID 23285067, 2012). "However, when we attempted to restore these effects through E2 supplementation, E2 pellets neither restored the anti-obesity effects in OVX FoxO1-KOMPOA females nor produced anti-DIO effects in naive FoxO1-KOMPOA males." (PMID 40667056, 2025). "However, in obesity, the impaired PI3K/Akt signaling leads to unphosphorylated FOXO1, which remains localized in the nucleus, promoting the transcription of genes involved in glucose generation (e.g., G6Pase and PEPCK) and lipid storage, leading to hyperglycemia and adiposity." (PMID 40218884, 2025). "Liver specific knockout of either FOXO1 alone or FOXO1/3/4 together led to lower blood glucose levels under both fasting and non-fasting conditions in mice, which also indicates FOXO may play an important role in obesity." (PMID 37656229, 2023). "JNK is a cell stress signaling marker regulating cell survival, but in the context of obesity and hypothalamic dysfunction it is involved in insulin receptor substrates (IRS) and recruitment of protein kinase B (AKT) and insulin-dependent translocation of forkhead box protein O1 (FoxO1)." (PMID 34578967, 2021). "Thus, in obesity, the animals presenting an increase in the hypothalamic MKP-3 also demonstrated a decrease in the phosphorylation of FoxO1 (by 54%, t = 2.88, df = 10, p = 0.0451) and Erk1/2 (by 51%, t = 4.900, df = 8, p = 0.0006), corroborating our previous data." (PMID 29062272, 2017). "However, the hypothalamic interaction between MKP-3 and FoxO1 during obesity was not investigated yet." (PMID 29062272, 2017).
Obesity (continued). "We further examined whether the diminished binding of CtBP2 observed in obesity is specific to FoxO1 and SREBP1 by detecting the interaction of CtBP2 with a known partner, zinc-finger protein FOG family member 1 (ZFPM1), that was again decreased in the liver of obesity (~96%)." (PMID 34728642, 2021). "More importantly, FOXO1, CSNK1A1, NF1L3 and NR1D1 clock genes/proteins are not involved in this type of obesity." (PMID 39062927, 2024). "These conditions are potentially additive in progressed obesity, although the effects of OGT activity on non-gluconeogenic FOXO1 gene expression (e.g. MTTP) have not been tested." (PMID 36111295, 2022). "Therefore, as obesity alone does not elicit HFpEF, the mechanistic underpinnings of obesity-induced cardiomyopathy are different from those in HFpEF, supporting a model in which FoxO1 overactivation in HFpEF leads to the detrimental functional consequences of cardiomyocyte lipid accumulation." (PMID 33727534, 2021). "On the other hand, we could not exclude the possibility that FOXO1 is not the only target of BATSP1; other BATSP1 target genes may also have functional roles related to obesity." (PMID 38010450, 2023).
prostate carcinoma (110 papers, 2007 to 2025). A carcinoma that arises from epithelial cells of the prostate gland. "Validation at the protein level confirmed that upregulation of GALNT7 in prostate cancer cells promotes loss of FOXO1 protein." (PMID 36725887, 2023). "In previous studies, the close association of lower FOXO1 levels with human cancers such as hepatocellular carcinoma, colorectal cancer, pancreatic cancer, prostate cancer, and lung cancer have been demonstrated." (PMID 35309123, 2022). "Studies have also shown that prostate cancer is associated with elevated expression of miR-96 and subsequent down regulation of FOXO1, a phenomenon that can be leveraged to control cell proliferation." (PMID 33869675, 2019). "Forkhead box transcription factor-1 (FOXO1) is a tumor suppressor that is often transcriptionally downregulated in human cancers such as prostate cancer although the underlying regulatory mechanisms remain elusive." (PMID 31410199, 2019). "Current studies report that AKT and its underlying signal FOXO1 negatively regulate Runx2 transcription in osteosarcoma and prostate cancer cells." (PMID 30486861, 2018). "Phosphatase and tensin homolog (PTEN) is often lost in prostate cancer which would also lead to loss or decreased function of downstream effectors such as FOXO1." (PMID 23951320, 2013). "FOXO1 only appears in the pathways of Module 4, it is associated with prostate cancer and insulin signaling pathway." (PMID 20419126, 2010). "Our findings suggest that EZH2 repression of expression of the FOXO1 tumor suppressor can be targeted by EZH2 inhibitor as a monotherapy for PTEN-proficient cancers or in combination with taxane for treatment of PTEN-deficient prostate cancers." (PMID 31410199, 2019). "The pivotal role played by FoxO transcription factors is corroborated by the finding that in humans the FOXO1 gene is positioned within a DNA region that is deleted in prostate cancer, and reduced levels of FoxO1 are associated with prostate cancer as well as Ewing’s sarcoma." (PMID 30646603, 2019). "Association of miR-96 and FOXO1 expression in prostate cancer specimens." (PMID 24260486, 2013). "FOXO1 is downregulated in prostate cancer cells; which is likely to be linked to upregulation of miR-370 in prostate cancer cells, which would reduce expression of the miR-370 target gene FOXO1." (PMID 23029264, 2012). "In the transcriptional regulation network, TP63 and FOXO1 act as suppressors of prostate cancer lineage plasticity, whereas RORC exerts a promoting effect." (PMID 38778150, 2024). "Based on all the information presented above, TP63 and FOXO1 suppress prostate cancer lineage plasticity through the RTK/RAS pathway, whereas RORC drives prostate cancer lineage plasticity through RTK/RAS pathway." (PMID 38778150, 2024). "Previous studies have shown that FoxO1 inhibits the androgen-independent activation of AR in prostate cancer." (PMID 39075471, 2024). "As an illustration, in prostate cancer, FOXO1 is often observed to be downregulated at the transcriptional level." (PMID 37894854, 2023). "Analysis of The Cancer Genome Atlas Prostate Adenocarcinoma (TCGA PRAD) cohort revealed a significant correlation between the GALNT7 and FOXO1 genes in clinical prostate cancer tissue." (PMID 36725887, 2023). "FOXO1 has an inhibitory impact on prostate cancer which is lost following phosphorylation and cytosolic migration." (PMID 36768610, 2023). "As the target genes of miR-96, FOXO1 and FOXO3a exert a protective effect against prostate cancer, while inhibition of FOXO1 and FOXO3a expression by transfected siRNAs led to an increase in the number of cancer cells." (PMID 37965449, 2023). "FOXO1 is an important negative regulator of the cell cycle that is often lost or downregulated in prostate cancer." (PMID 36725887, 2023). "Statins decrease cell proliferation and induce cell apoptosis, possibly mediated through the downregulation of AKT/FOXO1 phosphorylation in prostate cancer cells." (PMID 37760764, 2023).
prostate carcinoma (continued). "In this context, methylseleninic acid (MSA), a chemical compound previously demonstrated to reactivate FOXO1 in prostate cancer, was evaluated in Ewing sarcoma cells." (PMID 37894854, 2023). "FOXO1 has previously been identified as a possible tumour suppressor in prostate cancer cells and glioma cells by upregulating proapoptotic factors." (PMID 37254212, 2023). "On the other side, in prostate cancer, miR-486-5p induces different oncogenic pathways through the negative regulation of tumor suppressors such as FOXO1, PTEN, and SMAD2." (PMID 35337095, 2022). "IGF-1 is also implicated in castration-resistant PCa and has been shown to activate androgen receptor (AR) signaling in prostate cancer cells via the IGF-1R-forkhead box protein O1 (FOXO1) signaling axis." (PMID 35370981, 2022). "In this line, we confirmed the transcriptional control of GNMT by FOXO1 using shRNA against the transcription factor in prostate cancer cells." (PMID 35197445, 2022). "Weighted gene co-expression network analysis (WGCNA) suggests a set of five dysregulated hub genes (MAF, STAT6, SOX2, FOXO1, and WNT3A) that played crucial roles in biological pathways associated with prostate cancer progression." (PMID 35719950, 2022). "A new inhibitory target and FOXO1 is a key mediator of EZH2 inhibition to induce prostate cancer cell death." (PMID 34149432, 2021). "The FOXO1 analog peptide can be combined with IQGAP1 as endogenous FOXO1, inhibiting feedback activation of ERK upon transfection of FOXO1, and improving the sensitivity of prostate cancer cells to PI3K inhibitors and paclitaxel." (PMID 34123834, 2021). "These hormones can stimulate prostate cancer proliferation through activation of the FOXO1 subunit of the androgen receptor." (PMID 33921222, 2021). "In future studies, we will collect more prostate cancer patient samples to explore the correlation between FOXO1 expression and clinical parameters (including clinical stage, age, and survival time)." (PMID 34552661, 2021). "MiR-486-5p has been found to suppress key signaling proteins including FOXO1, which can contribute to prostate cancer progression." (PMID 34199766, 2021). "Here, we provided evidence that PLK1-dependent phosphorylation of FOXO1 induces its nuclear exclusion and negatively regulates FOXO1′s transcriptional activity in prostate cancer (PCa)." (PMID 32704044, 2020). "miR-96-5p was found to be abnormally expressed in colorectal cancer, prostate cancer, and several other malignant tumors where miR-96-5p can regulate FoxO1 levels and consequently inhibit proliferation." (PMID 32766159, 2020). "In prostate cancer, an activated nuclear AR binds to and reduces the DNA binding capacity of FOXO1 in an Akt-independent manner, affecting the expression of the proapoptotic genes, such as Fas." (PMID 32372224, 2020). "Paradoxically, the nuclear localization of FOXO3 was found to promote cell growth and tumor angiogenesis in neuroblastoma, and FOXO1 was shown to promote the transcription of VEGF-C in a prostate cancer cell line." (PMID 32629884, 2020). "Specifically, FOXO3 and FOXO1 are found to be deleted in approximately 15% to 20% of patients with prostate cancer." (PMID 32629884, 2020). "A prior research indicated that the downregulation of FOXO1 elevated tumorigenesis and invasion of prostate cancer cells." (PMID 32694937, 2020). "At the molecular level, a study shows that the Akt signalling pathway suppresses cell migration and invasion through FOXO1 to inhibit runt-related transcription factor 2 (RUNX2) transcriptional activity in prostate cancer." (PMID 32372224, 2020). "In prostate cancer, FOXO mutations are rare (<0.5% incidence), however FOXO1 and FOXO3 deep deletion is a frequent event, occurring in up to 15.2% and 13.4% of patients respectively." (PMID 32630372, 2020).